FADD (Fas associated via death domain)
Diseases named in the same sentence as FADD in open-access papers (continued):
Sharing a sentence is not in itself a finding about the gene and the disease.
cancer (continued). "It is important to note that even when cancer cells are resistant to TRAIL, exposure activates the secretion of the immune-suppressive cytokines, IL8, CXCL1, CXCL5, and CCL2 in a FADD-dependent way." (PMID 34371753, 2021). "On the contrary, double knocked out cells RIP3/FADD and MLKL/FADD were sensitive and RIP3/FADD revealed the highest sensitivity of all cell lines to treatment with anti-cancer drugs." (PMID 33800107, 2021). "More recently, FADD has been shown to play a key emergent role in the regulation of cell proliferation—via cell cycle control—and signalosome complexes, such as the necroptosome and the inflammasome, which could better explain its implication in cancer poor prognosis." (PMID 32847023, 2020). "We chemically conjugated purified FADD protein with cell permeable TAT (transactivator of transcription) peptide, to deliver in cancer cells." (PMID 32961826, 2020). "In this study, we chemically conjugated human FADD protein with TAT peptide for delivery into cancer cells and investigated the potential of the TAT conjugate FADD (TAT-FADD) in the regulation of apoptosis and NF-κB signaling." (PMID 32961826, 2020). "In cancer cells, the DED-containing protein cFLIPL (cellular FLICE inhibitory protein) competitively exclude caspase-8 binding to FADD at DISC and inhibits apoptosis signaling." (PMID 32961826, 2020). "As expected, tumour-specific delivery of FADD through a recombinant Salmonella strain, VNP-FADD, combined with low-dose ADT-OH treatment significantly inhibited tumour growth and induced cancer cell apoptosis." (PMID 31949127, 2020). "To date, some mechanisms by which cancer cells developed resistance to TRAIL have been elucidated, including the dysfunction of DR4 or DR5, defects in FADD and the overexpression of anti-apoptotic proteins such as c-FLIP, Bcl-2 and Survivin." (PMID 31864387, 2019). "Cancer-related genes including ANO1, CCND1, CTTN, FADD and ORAOV1 are involved in tumour cell proliferation, evasion of apoptosis, invasion, and migration." (PMID 28384287, 2017). "We recently showed that tumor cell-expressed TRAIL and TRAIL-R2 promote cancer progression, invasion, and metastasis by cancer cell-autonomous activation of Rac1 via the MPD of TRAIL-R2 independently of FADD." (PMID 28212753, 2017). "The present study indicates that CCA cancer cells can modulate apoptotic machinery by the modulation of Fas/FasL pathway and the c-FLIP/FADD cascade." (PMID 29089545, 2017). "More recently, FADD expression and phosphorylation were reported to be pro-tumorigenic in oncogenic KRAS-driven cancers." (PMID 27556297, 2016). "PTEN activation and PEA-15 dephosphorylation promote Fas-induced apoptosis by releasing FADD, and suppress ERK dependent proliferation in cancer cells." (PMID 26263999, 2015). "In some cancer cells, it was shown that interaction of extracellular PAR-4 with cell-surface GRP78 induces apoptosis in a FADD-dependent manner." (PMID 26246468, 2015). "Two other genes in the amplicon, FADD, and PPFIA1, displayed higher overall correlation across cancer types, implicating these genes as potential novel cancer drivers for further investigation." (PMID 24874471, 2014). "The extrinsic pathway of the apoptosis of human cancer cell lines MCF-7 and MDA-MB-231 after the SAMC treatment was revealed by the increase of FADD (fas) and the activation of caspase-8." (PMID 25070343, 2014). "Furthermore, analysis of transcriptomic data from the CCLE revealed that FADD, a critical mediator in the TLR2-induced apoptosis pathway, was enriched in cancer cells sensitive to UNE-C1." (PMID 39669578, 2024). "In addition, FADD and ZBP1 played a crucial role in various cancer-related pathways, such as the MAPK, WNT, and MTOR signaling pathways." (PMID 38684755, 2024). "Furthermore, our findings revealed that cancer cells expressing high levels of TLR2 and FADD are particularly sensitive to ICD induction by UNE-C1." (PMID 39669578, 2024).
cancer (continued). "On the other hand, we identified that high FADD expression might inhibit the immune process via regulating NK cells and TIL, which contributed to immune escape of cancer cells." (PMID 38684755, 2024). "Our result identified the FADD, TNFRSF1A, CASP9, MLKL, and CASP4 involved in the PANoptosis process and significantly affect patient survival, which can provide future direction in cancer research." (PMID 36874021, 2023). "Survival analysis showed that CNVs of TNF in 22 cancer types, TLR3 in 10 cancer types, RIPK1 in 9 cancer types, FAS in 8 cancer types, FADD in 8 cancer types, RIPK3 in 7 cancer types, MLKL in 6 cancer types, and FASLG in 5 cancer types were significantly associated with overall prognosis." (PMID 35748782, 2022). "Meanwhile, homozygous CNV analysis showed that FADD in 22 cancer types, FASLG in 25 cancer types, RIPK1 in 22 cancer types, TLR3 in 15 cancer types, TNF in 23 cancer types, FAS in 15 cancer types, MLKL in 12 cancer types, and RIPK3 in 17 cancer types had homozygous amplifications." (PMID 35748782, 2022). "Although the detailed mechanisms of FADD involved in apoptosis are still not fully elucidated, it has exhibited great potential as a valuable target for cancer treatment." (PMID 36348274, 2022). "The different effect of anti-cancer drugs and TNF-α/SM treatment on FADD-deficient cells shows that the response of cells depends not only on the activity of signaling pathways but also on the drug used." (PMID 33800107, 2021). "The results included well-known cancer genes such as MYC, FOXA2 and FADD, and the unknown SLITRK3 gene." (PMID 35006496, 2021). "Later studies reported non-apoptotic or pro-survival functions for FADD beyond T cells, to include cancer cells." (PMID 32194778, 2020). "Although non-apoptotic functions of FADD were first reported more than 15 years ago, reports of non-apoptotic functions of FADD in cancer is limited and there are no reports on the non-apoptotic functions of FADD in OS." (PMID 32194778, 2020). "In this study, we chemically conjugated FADD protein with TAT peptide for delivery into cancer cells and investigated its effectiveness in instigating apoptosis signaling and regulation of NF-κB activation in cancer cells." (PMID 32961826, 2020). "Absence of FADD expression has been suggested as marker of tumor development in mice and cancer prognosis in humans, due to the involvement of this protein with cell apoptosis, survival and proliferation." (PMID 33076854, 2020). "These drugs may upregulate the expression of DRs and FADD or downregulate anti-apoptotic proteins such as c-FLIP, XIAP or Survivin to enhance the effect of TRAIL and induce apoptosis of cancer cells." (PMID 31864387, 2019). "Based on these reports and our observed requirement of FADD for TRAIL-mediated cytokine induction, we next investigated whether cancer cell-expressed FADD would affect tumor growth in vivo." (PMID 28212753, 2017). "Additional studies are needed to identify the other crucial proteins in the apoptosis module, such as FADD, TARDD and PARP, which might provide more possible potential targets for cancer therapy and prevention." (PMID 27129147, 2016). "We found an inadequate expression of FADD and elevated expression of cFLIPL in cancer and transformed cells as compared to non-cancerous NIH 3T3 cells." (PMID 26972597, 2016). "The fact that FADD, a target of HPV, is a negative regulator of RIPK3-mediated necrosis may explain the strong necroptotic response in HPV-positive cancer cells that express RIPK3." (PMID 25888634, 2015). "On the other hand, p-FADD was apparently elevated in nine samples (64%) out of total 14 cancer tissues, while total FADD was not much changed." (PMID 24548998, 2014). "We recently showed that absence of FADD protein expression in cancer cells is also a relevant phenomenon in human malignancies." (PMID 15717929, 2005). "In addition, FADD could prevent the spontaneous expression of ZBP1, and then inhibit necroptosis of cancer cells." (PMID 38684755, 2024).
cancer (continued). "For example, FADD expression may be increased in certain types of solid tumors (such as LUAD, glioma, and hepatocellular carcinoma), which may lead to enhanced cell death signaling and prevent the growth of cancer cells." (PMID 37671047, 2023). "Recruitment of FLIP and FADD are important mediators in nonapoptotic cancer-promoting functions." (PMID 35249111, 2022). "However, the detailed mechanisms of FADD dysregulation involved in cancer progression are still not fully understood." (PMID 36348274, 2022). "In that case, the application of the RIP3 or MLKL inhibitors to the cells with non-functional FADD might support the effect of anti-cancer drugs on the principle of synthetic lethality." (PMID 33800107, 2021). "Later studies reported non-apoptotic functions for FADD in normal cells and cancer cells." (PMID 32194778, 2020). "The fact that the presence of FADD in tumor cells enhances cancer cell growth in vivo, but not in vitro, suggested that FADD might favor tumor growth by enabling an interaction with the tumor microenvironment." (PMID 28212753, 2017). "Cancers with a HPV-based etiology are reported to lesser frequency of genetic changes, in this study although the overall differential expression pattern of the genes in the patients did not correlate to HPV status, FADD showed a significant association." (PMID 26808319, 2016). "Absence of FADD expression could confer multiple growth advantages on cancer cells, and is expected to contribute to disease progression." (PMID 15717929, 2005). "However, the exact FADD mechanisms involved in cancer progression are still not fully understood." (PMID 36348274, 2022). "However, the role of FADD in cancer is controversial, but apparent discrepancies between studies could be explained by the fact that FADD exhibits both apoptotic and non-apoptotic roles." (PMID 36499482, 2022). "Available FADD and caspase-8 may recruit and stabilize TRAF2 (and perhaps other unknown proteins), resulting in the activation of ERK and JNK signaling and subsequent AP-1-dependent expression and activation of MMPs (e.g., MMP1) and final promotion of invasion and metastasis of cancer cells." (PMID 26510914, 2015). "3u can upregulate TNFR1, TNFR2, DR4, DR5, and FADD, so MCF7 is not as sensitive as other cancer cell lines to 3u." (PMID 30274263, 2018). "The protein levels of TRAF2 and TRAF6 were reduced in cancer cell lines treated with NA, but not TRAF3, TRADD, and FADD." (PMID 25575821, 2015). "This dependence on FADD was not contingent on the expression of Fas, TRAIL, or TNF-α, suggesting that even in the absence of ligand and/or receptor, some NPs could still activate death receptor extrinsic pathway to selectively target cancer cells to apoptosis." (PMID 25883673, 2015).
tumor (141 papers, 2003 to 2026). "Upregulated FADD is associated with worse prognosis, immune exhaustion, and tumor malignancy in LUAD patients." (PMID 37671047, 2023). "Alternatively, tumor cells upregulate the dominant-negative Fas-associated death domain (FADD) or intracellular FADD-like inhibitory protein (FLIP)." (PMID 37509316, 2023). "In conclusion, this study suggests that upregulated FADD is associated with worse prognosis, immune exhaustion, and tumor malignancy in patients with LUAD." (PMID 37671047, 2023). "While TNFR1, FADD and caspase-8 have been crucially implicated in the killing of tumor cells by CD8+ T cells and NK cells, the LUBAC components were found to antagonize the latter." (PMID 38020877, 2023). "In vitro, AFP has been proven to have an oncogenic effect by regulating TNF cytotoxicity, suppressing NK cell activity, and promoting tumor growth by reducing levels of FAS-associated death domain protein (FADD)." (PMID 37108802, 2023). "Potential associations between FADD and tumor malignancy, the immune microenvironment, genomic stability, and treatment sensitivity in LUAD patients were revealed by systematic bioinformatics analysis." (PMID 37671047, 2023). "The reduction of FADD phosphorylation was negatively associated with the proliferation capacity and tumor aggressiveness." (PMID 36348274, 2022). "FADD is not only linked to apoptosis but also proliferation, innate immunity, tumour growth, inflammation, and autophagy." (PMID 36186436, 2022). "The DR4/DR5 and TRAIL complex activates programmed cell-death signaling by stimulating the FAS-associated death domain protein (FADD) and the caspase-8 proenzyme, leading to apoptosis and tumor cell death." (PMID 34641520, 2021). "We saw protection against tumor challenge, with significant differences in tumor size between mice receiving FADD‐deficient DCs and WT DCs." (PMID 32663380, 2020). "Nevertheless, our data suggest that FADD‐deficient DCs can help to generate an antitumor inflammatory microenvironment that enhances the activation of T cells to clear the tumor." (PMID 32663380, 2020). "To see if FADD‐deficient DCs can protect mice from tumor challenge better than WT DCs, we first used the B16‐F10‐OVA subcutaneous model." (PMID 32663380, 2020). "In two separate tumor models, we find that mice receiving FADD‐deficient DCs as vaccine rejected tumors significantly better than those receiving a WT DC vaccine." (PMID 32663380, 2020). "We concluded that a combined treatment of anti‐PD‐1 antibodies and FADD‐deficient DCs can significantly protect mice from tumor challenge in a synergistic pattern." (PMID 32663380, 2020). "Mice receiving FADD‐deficient DCs post‐tumor challenge exhibited reduced tumor growth and 50% of them survived 19 days after tumor challenge compared to 5% of those receiving wild‐type DCs." (PMID 32663380, 2020). "FADD‐deficient and WT mouse DCs loaded with the relevant tumor peptide were injected onto mice before or after the syngeneic tumor challenge." (PMID 32663380, 2020). "Our results demonstrate that FADD‐deficient DCs can promote a strong T‐cell‐dependent antitumor response that is effective against two tumor models." (PMID 32663380, 2020). "Dampening NRF1 degradation under hypoxia not only impairs the polarization of TAMs, but also promotes tumor cells to become more susceptible to apoptosis in a FADD-dependent fashion, resulting in secondary necrosis due to the impairment of efferocytosis." (PMID 30833558, 2019). "Another study reports the interaction with and activation of FADD promoter by BRCA1, suggesting that BRCA1 loss or inactivation in a tumor can cause reduced levels of FADD that in turn desensitize cells to apoptosis." (PMID 31569512, 2019). "Over-expression of FADD or its variants can self-induced apoptosis of tumor cells, making the potential of FADD or its variants used as anti-tumor agents." (PMID 27767039, 2016).
tumor (continued). "FADD is much more than an instrument of death and implicated in embryonic development, cell proliferation, tumor progression, inflammation, necrosis, and autophagy." (PMID 27013580, 2016). "Increasing evidence shows that defects in FADD protein expression are associated with tumor progression both in mice and humans." (PMID 15717929, 2005). "In addition to its role in necroptosis, FADD has been implicated in promoting tumorigenesis by regulating cell cycle progression, enhancing proliferation, and inhibiting apoptosis, making it a tumor-favoring factor." (PMID 40740228, 2025). "Contrary to the progression of tumours, pre-miR-675 has also been shown to suppress tumour growth by binding to Fas-associated protein with death domain (FADD) and inhibiting its activity in cellular apoptosis, thus promoting necroptosis in human hepatocellular carcinoma cell lines." (PMID 37624037, 2023). "To validate tumor-suppressive effects of FADD loss (or oncogenic potential of FADD), we performed rescue experiments by overexpressing FADD or FADD-D (Serine 194 permanently replaced by Asparagine, mimicking pFADD which is a phosphorylated form of FADD at Serine 194) in FADD-/- Jurkat cells." (PMID 35637951, 2022). "Other H2S donors, diallyl trisulfide (DATS) and 5-(4-hydroxyphenyl)-3H-1,2-dithiole-3-thione (ADT-OH), are also effective in the suppression of tumor growth through inhibition of NF-κB activity and upregulation of Fas-associated protein with death domain (FADD) in melanoma." (PMID 34207284, 2021). "Taken all these data together, we conclude that the accumulated NRF1 can sustain the expression of FADD under hypoxia, which may enhance the susceptibility of tumor cells in response to extrinsic death stimuli, such as TRAIL, and lead to increased apoptosis." (PMID 30833558, 2019). "In order to engineer the VNP20009 for tumor-specific delivery of FADD and N-FADD, the coding sequences of mouse FADD and its variant N-FADD were cloned into the plasmid pQE30-NirB, in which the expression of the recombinant proteins was driven under the control of a hypoxia-inducible NirB promoter." (PMID 27767039, 2016). "Recently, emerging evidences have shown that FADD expression was associated with tumor development." (PMID 27013580, 2016). "Therefore, targeted delivery of FADD or its variants into tumor cells determines their antitumor efficacy." (PMID 27767039, 2016). "Furthermore, high FADD protein expression was associated with younger age at diagnosis (P = 0.034) and a higher grade of tumor differentiation (P = 0.011)." (PMID 27764170, 2016). "For the apoptosis deficiency in tumor cells, we hypothesized that tumor-specific delivery of FADD or its variant by VNP20009 with the potential to enhance apoptosis and improve the antitumor effect of VNP20009." (PMID 27767039, 2016). "It has been reported that MV-Edm can induce apoptosis in both the tumor cells and the syncytia by a series of signal pathways, such as the Fas-associated death domain (FADD), protein kinase C (PKC), and the janus kinase-signal transducer and activator of transcription (JAK-STAT) signaling pathways." (PMID 23009685, 2012). "In addition, significant associations were also seen for tumor grade with Fas, FADD, and caspase 10, and for tumor stage with Fas expression." (PMID 19728877, 2009). "FADD deficient tumor cells resist death receptor-mediated apoptosis by chemotherapeutics drugs." (PMID 19513126, 2009). "FADD has been implicated in cell survival as well as growth control, and consequently it may play a role in tumor progression." (PMID 18823530, 2008). "If our hypotheses are correct, then activated TIL that express death ligands could contribute to FADD-deficient tumor proliferation." (PMID 15717929, 2005).